JOSD2 (Josephin domain containing 2)
Description:
Cleaves 'Lys-63'-linked poly-ubiquitin chains, and with lesser efficiency 'Lys-48'-linked poly-ubiquitin chains (in vitro). May act as a deubiquitinating enzyme.
Synonyms: SBBI54
Tractability: Small molecule: a structure with a bound ligand is known. PROTAC: ubiquitination databases record sites on it; its protein half-life has been measured.
Target class: Enzyme; Hydrolase
Gene: Protein-coding gene on chromosome 19 (50,505,995 to 50,514,675, reverse strand). Ensembl gene ENSG00000161677.
Subcellular location: Cytoplasm, cytosol
Pathways (Reactome):
Metabolism of proteins: Josephin domain DUBs
Gene Ontology:
Molecular function: cysteine-type deubiquitinase activity; protein binding; deubiquitinase activity
Biological process: protein deubiquitination
Cellular component: cytosol; cytoplasm
Genetic constraint (gnomAD): Loss-of-function variants: 20 observed, 19.07 expected, observed/expected ratio (o/e) 1.05, 90% interval 0.74 to 1.52. The upper end of that interval is the gene's LOEUF score, 1.52, which puts it in group 6 of 6, group 1 being the genes least tolerant of losing a copy. Missense variants: 215 observed, 237.27 expected, observed/expected ratio (o/e) 0.91, 90% interval 0.81 to 1.01. Synonymous variants: 118 observed, 115.96 expected, observed/expected ratio (o/e) 1.02, 90% interval 0.88 to 1.19.
Homologues: Orthologues: chimpanzee JOSD2 (99% identical), macaque JOSD2 (98% identical), dog JOSD2 (96% identical), mouse Josd2 (95% identical), guinea pig JOSD2 (94% identical), rat Josd2 (93% identical), pig JOSD2 (81% identical), zebrafish josd2 (61% identical), tropical clawed frog josd2 (60% identical), Drosophila melanogaster Josd (49% identical), Caenorhabditis elegans josd-1 (37% identical). Paralogues in human: JOSD1 (54% identical).
Diseases named in the same sentence as JOSD2 in open-access papers:
JOSD2 is named in the same sentence as 17 diseases in open-access papers, as found by Europe PMC text mining. Sharing a sentence is not in itself a finding about the gene and the disease. The quoted sentences say what the papers report.
acute myeloid leukemia (3 papers, 2022 to 2025). Acute myeloid leukemia (AML) is a group of neoplasms arising from precursor cells committed to the myeloid cell-line differentiation. "JOSD2 influences the proliferation and progression of hepatocarcinoma, lung cancer, and esophageal squamous cell carcinoma and modulates acute myeloid leukemia progression." (PMID 41009814, 2025). "JOSD2 inhibits nuclear localisation by reducing the lysine 433 acetylation of PKM2 in acute myeloid leukaemia (AML), thereby decreasing downstream gene expression and ultimately slowing AML progression." (PMID 39778006, 2025). "Here, we show that deubiquitinase JOSD2, a novel tumor suppressor, blocks PKM2 nuclear localization by reducing its K433 acetylation in acute myeloid leukemia (AML)." (PMID 35836282, 2022).
breast carcinoma (3 papers, 2022 to 2025). "Recent reports have documented that TAZ can be directly deubiquitinated and stabilized by USP1, USP10, OTUB2 and JOSD2 in hepatocellular carcinoma, breast cancer and cholangiocarcinoma." (PMID 35931679, 2022).
cholangiocarcinoma (3 papers, 2022 to 2024). A carcinoma that arises from the intrahepatic biliary tree (intrahepatic cholangiocarcinoma) or from the junction, or adjacent to the junction, of the right and left hepatic ducts (hilar cholangiocarcinoma). "Over-expressed JOSD2 was positively correlated with the worse prognosis in hepatocellular carcinoma, cholangiocarcinoma (CCA), and NSCLC." (PMID 36159990, 2022).
hepatocellular carcinoma (2 papers, 2022). A malignant tumor that arises from hepatocytes. "Furthermore, we analyzed the co-expression of ATXN3, JOSD1 and JOSD2 in hepatocellular carcinoma using the GSCALite database, and analyzed the signaling pathways involved by MJDs family member respectively." (PMID 36159990, 2022). "The sub-types of with the highest proprotion of all alterations were Hepatocellular carcinoma plus Intrahepatic Cholangiocarcinoma, Hepatocellular Adenoma, and Hepatocellular carcinoma for ATXN3, ATXN3L, JOSD1, and JOSD2, respectively." (PMID 36159990, 2022).
lung carcinoma (2 papers, 2024 to 2025). "To further validate the overexpression of JOSD2 in NSCLC, we performed IHC staining to evaluate the JOSD2 protein levels in a lung cancer tissue array consisting of 80 LUADs." (PMID 38177135, 2024).
breast tumor (1 paper, 2019). "Following the current study by TCSBN correlation analysis of SERTAD1 in cancer and normal tissue, SERTAD1 significantly correlated with JOSD2 (Corr = 6.15) and UBE2S (Corr = 0.588) in breast tumor and normal tissue respectively." (PMID 30857225, 2019).
colitis (1 paper, 2021). Inflammation of the colon. "Using the DSS-colitis model, they found that mice bearing NLRP3-R779C mutation in hematopoietic cells showed intensified colitis, which was ameliorated by downregulation of BRCC3 or JOSD2." (PMID 33808793, 2021).
non-small cell lung carcinoma (1 paper, 2022). A group of at least three distinct histological types of lung cancer, including non-small cell squamous cell carcinoma, adenocarcinoma, and large cell carcinoma. "In non-small cell lung cancer (NSCLC), deubiquitinase Josephin Domain-containing protein 2 (JOSD2) was recently identified to display comprehensive effects on glucose catabolism, and thereby promoting cancer cell proliferation." (PMID 35307036, 2022).
testicular tumors (1 paper, 2022). "Our results showed that ATXN3, JOSD1, and JOSD2 were markedly up-regulated in HCC samples, while ATXN3L was expressed only in testicular and testicular tumors." (PMID 36159990, 2022).
tumor (6 papers, 2020 to 2025). "JOSD2 deficiency inhibits tumor cell proliferation by reducing glycolysis, and its mRNA expression is related to the worst prognosis in NSCLC." (PMID 36159990, 2022). "These gain-of-function amplifications of JOSD1 and JOSD2 are thought to cause elevated expression to promote their tumor-promoting functions." (PMID 32982735, 2020). "By analysis, we found multiple tumor-related pathways were enriched, so we further examined the key effectors of these pathway upon depletion of JOSD2, and found that these cancer-associated pathways experienced varying degrees of upregulation or downregulation." (PMID 38177135, 2024). "More importantly, JOSD2 distinctly accelerated the in vivo tumor growth in NCI-H460 xenografted tumors harboring LKB1-WT, but exerting minimal impact in control and LKB1-3KR groups." (PMID 38177135, 2024). "JOSD2 depletion resulted in a robust inhibition of tumor formation in the NCI-H358 xenografted tumors." (PMID 38177135, 2024). "Taken together, the tumor-promoting effect of JOSD2 is dependent, at least partially, on its regulation on LKB1." (PMID 38177135, 2024). "Consistently, intratumor injection of lentiviral vector delivering JOSD2 shRNA significantly delayed the tumor growth of both PDXs in vivo." (PMID 38177135, 2024). "Nevertheless, both JOSD1 and JOSD2 expression have been found to be significantly alterated in several tumor types." (PMID 32982735, 2020). "Similarly, on a pre-existing NCI-H1299 tumor models, intratumor injection of lentiviral vector delivering JOSD2 shRNA exhibited significant suppressive effect on the tumor growth, with inhibition ratio as 59.72% (P < 0.001)." (PMID 38177135, 2024). "We then further ask whether the tumor-promoting effect of JOSD2 is dependent on its regulatory effect on LKB1." (PMID 38177135, 2024). "As the kinase activity is critical for LKB1 to exert its tumor suppressor function, we then examined whether JOSD2 imposes negative regulatory effect on LKB1 by measuring LKB1 kinase activity toward AMPKα in vitro." (PMID 38177135, 2024). "The IHC staining of JOSD2 was pending HCC tumor tissue analysis in the HPA." (PMID 36159990, 2022). "• JOSD1 and JOSD2 are amplificated in several tumor types and maybe potential therapy targets." (PMID 32982735, 2020). "The deubiquitinase JOSD2 is a novel tumour suppressor, and research has revealed that PKM2 is a new protein that interacts with JOSD2." (PMID 39778006, 2025). "Taken together, these data confirmed that depletion of JOSD2 significantly arrested the NSCLC cell proliferation in vitro and tumor growth in vivo." (PMID 38177135, 2024). "Mechanically, we found that JOSD2 restricts the kinase activity of LKB1, an important tumor suppressor generally inactivated in NSCLC, by removing K6-linked polyubiquitination, an action vital for maintaining the integrity of the LKB1-STRAD-MO25 complex." (PMID 38177135, 2024).
cancer (3 papers, 2019 to 2024). A tumor composed of atypical neoplastic, often pleomorphic cells that invade other tissues. "Nevertheless, there is emerging evidence indicating that Ataxin-3, Ataxin-3L, JOSD1, and JOSD2 are also implicated in cancer progression." (PMID 32982735, 2020). "In contrast, mutational alteration of JOSD1 and JOSD2 in cancer is less common." (PMID 32982735, 2020). "JOSD2 protein levels were significantly correlated with TNM stages of LUADs, as increasing JOSD2 expressions were associated with more advanced cancer stages." (PMID 38177135, 2024). "Recently, the roles of JOSD2 in malignant tumors have been gradually revealed." (PMID 38177135, 2024).
cardiovascular diseases (1 paper, 2025). "Recent studies have highlighted the involvement of DUBs such as USP25, JOSD2, and USP28 in cardiovascular diseases." (PMID 40192103, 2025).
JOSD2 also shares sentences with these, for which no sentence is quoted: cardiac hypertrophy (1 paper); esophageal squamous cell carcinoma (1); hepatocellular adenoma (1); intrahepatic cholangiocarcinoma (1); ovarian tumor (1).